NMD3 (NMD3 ribosome export adaptor)
Description:
Acts as an adapter for the XPO1/CRM1-mediated export of the 60S ribosomal subunit.
Synonyms: CGI-07
Tractability: PROTAC: ubiquitination databases record sites on it; its protein half-life has been measured.
Gene: Protein-coding gene on chromosome 3 (161,104,681 to 161,253,532, forward strand). Ensembl gene ENSG00000169251.
Subcellular location: Cytoplasm; Nucleus
Subcellular location (Human Protein Atlas): Nucleoli; Nucleoplasm
Gene Ontology:
Molecular function: protein-macromolecule adaptor activity; ribosomal large subunit binding; RNA binding
Biological process: positive regulation of protein localization to nucleolus; positive regulation of RNA biosynthetic process; ribosomal large subunit export from nucleus
Cellular component: cytoplasm; membrane; nucleolus; nucleoplasm; nucleus
Genetic constraint (gnomAD): Loss-of-function variants: 12 observed, 22.19 expected, observed/expected ratio (o/e) 0.54, 90% interval 0.35 to 0.88. The upper end of that interval is the gene's LOEUF score, 0.88, which puts it in group 3 of 6, group 1 being the genes least tolerant of losing a copy. Missense variants: 203 observed, 224.36 expected, observed/expected ratio (o/e) 0.9, 90% interval 0.81 to 1.02. Synonymous variants: 81 observed, 71.71 expected, observed/expected ratio (o/e) 1.13, 90% interval 0.94 to 1.36.
Homologues: Orthologues: chimpanzee NMD3 (99% identical), macaque NMD3 (98% identical), rabbit NMD3 (98% identical), mouse Nmd3 (95% identical), pig NMD3 (95% identical), dog NMD3 (95% identical), rat Nmd3 (93% identical), guinea pig NMD3 (84% identical), tropical clawed frog nmd3 (83% identical), zebrafish nmd3 (77% identical), Drosophila melanogaster Nmd3 (53% identical), Caenorhabditis elegans T25G3.3 (50% identical).
Diseases named in the same sentence as NMD3 in open-access papers:
NMD3 is named in the same sentence as 9 diseases in open-access papers, as found by Europe PMC text mining. Sharing a sentence is not in itself a finding about the gene and the disease. The quoted sentences say what the papers report.
Cognitive impairment (1 paper, 2020). Abnormal cognition is characterized by deficits in thinking, reasoning, or remembering. "The recessive and overdominant model of NMD3 rs34016896 was associated with cognitive impairment in PD patients." (PMID 31937261, 2020).
lung adenocarcinoma (1 paper, 2019). A carcinoma that arises from the lung and is characterized by the presence of malignant glandular epithelial cells. "According to the TCGA database, XPO1 and NMD3 genes are frequently altered in lung squamous cell carcinoma and to a less extent in lung adenocarcinoma." (PMID 31113936, 2019).
lung carcinoma (1 paper, 2019). "Lung cancer samples with XPO1 alteration tend to express higher level of NMD3." (PMID 31113936, 2019).
lung squamous cell carcinoma (1 paper, 2019). "Accordingly, mRNAs of XPO1 and NMD3 are high in lung squamous cell carcinoma." (PMID 31113936, 2019).
pancreatitis (1 paper, 2022). Inflammation of the pancreas. "In this study, these datasets were reviewed and we found a great number of genes that were differently expressed between pancreatitis samples and control samples, including murine Krt8 and Nmd3 (148 genes in AP models and 1195 genes in CP models)." (PMID 35958278, 2022).
toxicity (1 paper, 2025). The degree to which an agent can damage an organism. "It is noteworthy that all target antigens (ROCK2, TOM1L1, NMD3, CPT1A, and MIT3) are expressed in normal skin according to the Human Protein Atlas, consistent with a possible relationship between autoantibodies and skin toxicity." (PMID 40828987, 2025).
cancer (1 paper, 2025). A tumor composed of atypical neoplastic, often pleomorphic cells that invade other tissues. "Curiously, knocking down NMD3 confers protection against Portimine A in cancer cell lines, rather than eliciting the same effects as Portimine A." (PMID 39948420, 2025).
NMD3 also shares sentences with these, for which no sentence is quoted: Parkinson disease (1 paper); tumor (1).